WNT5A (Wnt family member 5A)
Diseases named in the same sentence as WNT5A in open-access papers (continued):
Sharing a sentence is not in itself a finding about the gene and the disease.
Obesity (continued). "Since previous studies have implicated WNT5A and WNT4 in adipogenesis, we hypothesized that WNT5A and WNT4 might influence obesity related traits and might be candidate susceptibility genes for obesity." (PMID 28272483, 2017). "Serum levels of Wnt5a were increased in patients with severe obesity." (PMID 23861788, 2013). "Until now data on wnt5a and sFRP5 in human subjects with obesity are limited." (PMID 22384249, 2012). "In agreement it has been shown in an animal model, that alterations in the locus of the wnt5a, the JNK1 and the PKC-delta gene are associated with obesity, suggesting that wnt5a acts as an important anti-adipogenic factor not only in cell culture systems but also in a whole body organism." (PMID 22384249, 2012). "Therefore, we hypothesize that SFRP5/WNT5A pathway in adipose tissue might play an important role in NAFLD-related to obesity pathogenesis through the adipose tissue-liver axis." (PMID 36077270, 2022). "Therefore, it is hypothesized that Sfrp5 and Wnt5a may also be involved in the pathogenesis of obesity and obesity-related disorders." (PMID 34371968, 2021). "Therefore, we propose that SFRP5 may exert a protective role in the pathogenesis of adipose tissue inflammation and obesity via non‐canonical WNT5A signalling pathway." (PMID 32004418, 2020). "Thus, manipulation the balance between Wnt5a and SFRP5 may represent a potential strategy for management of obesity-associated metabolic abnormalities." (PMID 31470850, 2019). "The mechanism behind the obesity-induced Wnt5a upregulation remains largely unknown." (PMID 27608847, 2016). "Serum Wnt5a, leptin, and TNF-α showed significantly higher levels in females with obesity than controls and a significant increase with higher classes of obesity." (PMID 39837875, 2025). "In conclusion, this study identified three markers, Wnt5a, leptin, and TNF-α which were significantly higher in women with obesity and positively correlated with each other." (PMID 39837875, 2025). "Individuals living with obesity in the current study exhibited higher circulating concentrations of IL-6 and higher HOMA2-IR scores in conjunction with downregulation of scWAT WNT5A mRNA expression." (PMID 35958557, 2022). "In the present study, fat-specific knockout of Wnt5a (Wnt5a-FKO) prevented HFD-induced increases in serum Wnt5a levels in male C57BL/6 J mice, which suggested adipocytes are primarily responsible for obesity-induced increases in Wnt5a levels." (PMID 35478181, 2022). "We aimed to evaluate the role of the SFRP5-wingless-MMTV integration site family member 5a (WNT5A) pathway, closely related to adipogenesis, in subcutaneous (SAT) and visceral adipose tissues (VAT) and its relationship with obesity-related NAFLD." (PMID 36077270, 2022). "In this study, our cohort of women made it possible to relate SFRP5, WNT5A and PPARγ mRNA abundance in SAT and VAT with obesity and NAFLD." (PMID 36077270, 2022). "Additional human studies will be required to shed light on the influence of Wnt5a/Sfrp5 in NAFLD and hepatic fibrosis observed in obesity." (PMID 34371968, 2021). "The circulating levels of Wnt5a and its expression in VAT are increased in obesity, contributing to systemic and local inflammation." (PMID 34680216, 2021). "Although WNT5A was reported to be able to regulate cell proliferation and adipogenesis via MAPK, data on the relationships between WNT5A and SFRP5 in humans with obesity are limited and inconsistent." (PMID 33192583, 2020). "In 2012, Schulte and collaborators reported a significant increase of both WNT5A and SFRP5 concentrations in patients suffering from obesity compared with lean patients." (PMID 33192583, 2020). "Pro‐inflammatory WNT5A and anti‐inflammatory SFRP5 both play pivotal roles in the development of obesity." (PMID 32004418, 2020). "Non-canonical signalling of WNT5A is reported to contribute to obesity-induced inflammation and systemic insulin resistance in obese mice independent of tissue expansion." (PMID 35958557, 2022).
Obesity (continued). "Conversely, noncanonical WNT5A signaling has been found to play an essential role in obesity-induced VAT inflammation and metabolic dysfunction, which can promote insulin resistance under conditions of overfeeding." (PMID 36077270, 2022). "SFRP5 is associated with comorbidities such as obesity, DM2, insulin resistance, and atherosclerosis, inhibiting the wingless-type family member 5a signaling (Wnt5a) and the non-canonical Wnt family and regulating the expression of pro-inflammatory cytokines." (PMID 33807959, 2021). "Similar report also indicated that SFRP5 expression was reduced in rodents with genetic or dietary obesity, while systemic administration of SFRP5 improved glucose tolerance and insulin resistance through inhibition of inflammatory responses and Wnt5a-JNK signaling." (PMID 31470850, 2019). "In this study we analyzed gene expression patterns in visceral and subcutaneous adipose tissue to gain insight into the potential role of non-canonical WNT5A/PCP signaling in adipose tissue inflammation in the setting of obesity." (PMID 29229927, 2017). "Considering the biological roles of WNT4 and WNT5A involved in adipogenesis, we aimed to investigate whether SNPs in WNT4 and WNT5A contribute to obesity related traits in Han Chinese population." (PMID 28272483, 2017). "The current study investigated the potential contribution of non-canonical WNT5A/PCP signaling to visceral adipose tissue (VAT) inflammation and associated metabolic dysfunction in individuals with obesity." (PMID 29229927, 2017). "At a biomolecular level, it has been reported that circulating WNT5a concentration is increased in human obesity and that noncanonical Wnt signaling is activated, probably contributing to the pro-inflammatory state in visceral adipose tissue." (PMID 26958939, 2016). "Moreover, they noted that after 24 weeks of nourishing a high-fat/high-sucrose diet for wild-type mice, leptin deficiency mice (ob/ob) and Zucker diabetic fatty mice (fa/fa) resulted in obesity phenotype, down-regulation of SFRP5 expression, and overexpression of WNT5A." (PMID 37542207, 2023). "Noncanonical Wnt5a signaling plays an essential role in obesity- or diabetes-induced metabolic dysfunction and inflammation, but its explicit molecular mechanisms and biological function in diabetic nephropathy (DN) remain unknown." (PMID 33462195, 2021). "It has been reported that circulating concentration of WNT5a are increased in human obesity and that noncanonical Wnt signaling is activated, probably contributing to the pro-inflammatory state in visceral adipose tissue and to the development of obesity-associated co-morbidities." (PMID 26958939, 2016). "WNT5a induces the non-canonical activation of JNK1, and SFRP5 deficient mice show highly activated JNK1 in HFD indicating that SFRP5 inhibits WNT5a mediated non-canonical JNK1 activation in adipose tissues to suppress obesity-induced inflammation and insulin resistance." (PMID 23781214, 2013). "It is not yet known whether the expression of IL6 mediated by Wnt5a/JNK is an extended mechanism to adipocytes of other species, including the mouse which is a model in many studies on the role of adipocytes in obesity and the associated pathologies to this disease." (PMID 35111744, 2021). "In patients with severe obesity, however, wnt5a was detectable in serum samples in the absence of any acute or chronic classical inflammatory or immune disease, which might suggest that wnt5a can be released from inflamed adipose tissue into systemic circulation." (PMID 22384249, 2012). "We recently reported that WNT5A, a WNT ligand that predominantly activates non-canonical WNT signaling contributes to obesity-induced adipose tissue inflammation and systemic insulin resistance in obese mice." (PMID 29229927, 2017).
leukemia (33 papers, 2008 to 2025). A malignant (clonal) hematologic disorder, involving hematopoietic stem cells and characterized by the presence of primitive or atypical myeloid or lymphoid cells in the bone marrow and the blood. "Out of 17 genes that mapped to the DISEASE database, 7 have been linked to pathogenesis of human CLL and/or other leukemias (Birc3, Wnt5a, SP140, Atr, Lyn, CD274, and Flt3), and SIFT analysis revealed that the detected mutation in Lyn is likely deleterious." (PMID 34417556, 2022). "This indicates that both cortactin and HS1 are involved in the capacity of Wnt5a to enhance leukemia-cell motility and that the deficiency of one cannot be fully compensated by the other." (PMID 30568170, 2019). "Analysis of human primary leukemia cases identified that a deletion of the WNT5A gene and/or loss of Wnt5a expression was present in the majority of the patient samples." (PMID 24944588, 2014). "Notably, WNT5A has been implicated in various malignancies, including leukemia, and its dysregulation can contribute to tumorigenesis." (PMID 40301374, 2025). "However, Wnt5a acts as an antitumor factor in leukemia, counteracting multiple oncogenic processes associated with the disease." (PMID 41282593, 2025). "There is evidence that β-catenin overexpression and its increased or constitutive activation drives leukemia initiation in some types of myeloid malignancies, which is associated with poor prognosis and can be associated to Wnt3a or Wnt5a activity." (PMID 32751131, 2020). "The lack of remission samples limits our study as we could not detect the methylation status of remission samples, but we can speculate that the loss of WNT5A may cause leukemogenesis and methylation restoration might help complete remission in patients with leukemia." (PMID 26316480, 2015). "A leukemia cell study also showed comparable findings, indicating that Wnt5a promoted movement and infiltration via the PI3K/Akt-RhoA pathway." (PMID 40373156, 2025). "In summary, we found that Wnt5a induces ROR1 to recruit and activate DOCK2, leading to activation of ERK1/2, which appears responsible for the capacity of Wnt5a to enhance leukemia-cell proliferation." (PMID 33097837, 2021). "Together, these studies provide rationales for the inhibition of Wnt5a/ROR1 signaling in patients with leukemia." (PMID 32751131, 2020). "There is evidence pointing at Wnt5a as a therapeutic molecule against leukemias; by inhibiting β-catenin-dependent signaling, it would promote differentiation and reduce aberrant proliferation." (PMID 32751131, 2020). "Previously we described that HS1 contributed to the capacity of Wnt5a to enhance leukemia-cell migration." (PMID 30568170, 2019). "When HL-60 leukemia cells were stimulated with the supernatant of adeno-Wnt5a MSCs, proliferation of leukemia cells highly reduced." (PMID 30705410, 2019). "We examined primary neoplastic cells of patients with MCL who had circulating leukemia cells for Wnt5a-induced, ROR1-dependent activation of Rac1." (PMID 29872501, 2018). "Wnt5a acts as a potential ligand for Ror1 and Ror22, 12, 13 and interaction between Ror1 and Ror2 is required for Wnt5a signaling, which promotes leukemia chemotaxis and proliferation." (PMID 28432357, 2017). "Wnt5a also promotes the expansion and self-renewal of apoptosis-resistant transgenic hematopoietic stem cells (HSCs), as well as the self-renewal of leukemia cells in vitro." (PMID 24959224, 2014). "In conclusion, the present study confirmed that bMSC-derived Wnt5a inhibits the proliferation of leukemia HL60 cells and promotes their maturation via activating the non-canonical and impairing the canonical Wnt signaling pathways." (PMID 24959224, 2014). "However, stimulation with Wnt5a significantly increased the invasive capacity of ROR1xTCL1 splenic leukemia cells compared to TCL1 leukemia cells." (PMID 40295829, 2025). "In leukemia B cells, we found that Wnt5a could upregulate MMP-9 expression via ROR1-dependent activation of NF-κB." (PMID 40295829, 2025).
leukemia (continued). "The increased expression of BCL2L1 induced by Wnt5a-activation of ROR1 may account in part for the enhanced resistance to venetoclax of leukemia cells that express high levels of ROR1." (PMID 35418613, 2022). "Treatment targeting Wnt5a-signaling may mitigate such effects, potentially enhancing the clearance of leukemia cells when used alone or in combination with drugs that target other survival-signaling pathways in CLL." (PMID 35210425, 2022). "Factors provided by the leukemia microenvironment, such as Wnt5a, may enhance resistance to venetoclax." (PMID 35418613, 2022). "Recent studies have demonstrated that Wnt5a could induce activation of Rac1 in leukemia cells of patients with CLL via a ROR1-dependent pathway, which could not be inhibited by ibrutinib." (PMID 29872501, 2018). "Wnt5a expression is downregulated via aberrant methylation in most acute leukemia cases, and is upregulated in non-malignant hematopoietic (NMH) and complete remission (CR) cases; thus, increased Wnt5a expression might act as a tumor suppressor in leukemia." (PMID 28380463, 2017). "However, like in endometrial carcinomas, WNT5A mRNA expression was downregulated in some malignant tumors and types of leukemia." (PMID 26316480, 2015). "The results showed that the proliferation of HL60 cells, a leukemia cell line, was significantly inhibited when the cells were stimulated with the culture supernatant of adeno-Wnt5a bMSCs compared with the culture supernatants of bMSCs and adeno-vector bMSCs for 24 or 48 h (P<0.01)." (PMID 24959224, 2014). "RT-PCR analysis of bone marrow (BM) patient B-ALL samples revealed expression of WNT5a in 42% of cases.T-ALL patient samples have also shown high expression of WNT5a, highlighting its role in leukemia progression." (PMID 40805157, 2025). "Relevant in this regard is the leukemia-cell expression of the receptor tyrosine kinase-like orphan receptor (ROR1), which can serve as a receptor for Wnt5a." (PMID 35418613, 2022). "Wnt5a can induce ROR1-dependent cell signals, thereby enhancing leukemia-cell proliferation, migration, and survival." (PMID 35210425, 2022). "This is notable as Wnt5a is an identified ligand for ROR1, an evolutionarily conserved and developmentally-restricted type-I surface protein, which is expressed by the leukemia cells of most patients with CLL." (PMID 33097837, 2021). "Wnt5a, a ligand for ROR1 and ROR2, induced ROR1/ROR2 hetero-oligomerization and enhanced leukemia chemotaxis and proliferation." (PMID 29856777, 2018). "In more recent studies on CLL cells, we described that Wnt5a could induce ROR1 to recruit and activate guanine exchange factors (GEFs), and thereby enhance leukemia-cell migration and proliferation." (PMID 30568170, 2019). "Collectively, these studies reveal that Wnt5a induces ROR1 to complex with cortactin/HS1/ARHGEF1 at P841, which induces phosphorylation of cortactin and HS1, activation of ARHGEF1 and RhoA, thereby enhancing leukemia-cell migration." (PMID 30568170, 2019). "Here we report our studies evaluating whether cortactin is recruited to ROR1 upon stimulation with Wnt5a, undergoes tyrosine phosphorylation, and recruits/activates ARHGEF1 to promote F-actin polymerization and leukemia-cell migration." (PMID 30568170, 2019). "Silencing Wnt5a, a non-canonical Wnt ligand, by methylation has been reported in some types of leukemia." (PMID 25428027, 2014). "Because the lymphocytes of healthy adults do not express ROR1, this pathway of Wnt5a-induced DOCK2 phosphorylation may be restricted to leukemia B cells." (PMID 33097837, 2021). "We also performed a cell invasion assay using splenic leukemia cells of TCL1 Tg or ROR1xTCL1 dTg mice in response to mouse CXCL12, without or with stimulation of Wnt5a." (PMID 40295829, 2025). "Prior studies using the leukemia cell-line, MEC1, found that these cells expressed Wnt5a, but not ROR1." (PMID 33097837, 2021).
leukemia (continued). "For instance, we could not address the mechanism of Wnt5a-mediated ROR1/2 hetero-dimerization in regulation of downstream signaling, which was previously shown to modulate leukemia chemotaxis and proliferation." (PMID 35504983, 2022).